SOD2 (superoxide dismutase 2)
Diseases named in the same sentence as SOD2 in open-access papers (continued):
Sharing a sentence is not in itself a finding about the gene and the disease.
Intellectual disability (1 paper, 2014). "The SOD2 Val16Ala polymorphism and complication with intellectual disability were found to be significant covariates influencing the intercept of the logit function for the probability of an elevated γ-GT level." (PMID 25372290, 2014). "During the forward-inclusion and the backward-elimination analyses, the SOD2 Val/Val genotype, complication with intellectual disability and co-administered CBZ, PB and PHT were found to be significant covariates influencing the BASE of the logit (Pr)." (PMID 25372290, 2014).
latent infection (1 paper, 2022). "SOD2 is often upregulated by proinflammatory cytokines, however, this seems incompatible with latent infection which overall simulates an anti-inflammatory microenvironment." (PMID 35215840, 2022).
Lissencephaly (1 paper, 2023). A spectrum of malformations of cortical development caused by insufficient neuronal migration that subsumes the terms agyria, pachygyria and subcortical band heterotopia. "While promoting differentiation (SOD2 activation), RA also inhibits cell migration and invasion by decreasing doublecortin and lissencephaly-1." (PMID 38249515, 2023).
lysosomal disorder (1 paper, 2025). "Previous research has demonstrated that lysosomal disorder is involved in PM2.5-induced ferroptosis and oxidative regulation, and the reduction of Sod2 contributes to lysosomal membrane permeabilization." (PMID 39949511, 2025).
malnutrition (1 paper, 2021). Inadequate nutrition resulting from poor diet, malabsorption, or abnormal nutrient distribution. "An increase in the superoxide level in the plasma and a decrease in SOD‐2 protein expression in both muscles were observed in the malnutrition group." (PMID 33650806, 2021). "The expression level of SOD‐2 protein was significantly lower in both the plantaris and soleus muscles of the malnutrition group than that in the control group." (PMID 33650806, 2021). "In addition, the level of SOD‐2 protein expression decreased in the plantaris and soleus muscles, and the level of the malondialdehyde concentration increased in the soleus muscle in the malnutrition group." (PMID 33650806, 2021).
melasma (1 paper, 2022). "TheWNT3A, EDN3, ESR2, PTG2, MMP1, and SOD2 genes were up-regulated, whereas the COL4A1, CSF2, DKK3, COL7A1, TIMP4, CCL2, and CDH11 genes were down-regulated in melasma skin fibroblasts when compared to the ones from adjacent healthy skin." (PMID 35840442, 2022).
metastatic prostate carcinoma (1 paper, 2013). A carcinoma that arises from the prostate gland and has spread to other anatomic sites. "In addtion, the identified interactions in metastatic prostate cancer contain several experimentally confirmed targets of hsa-miR-143 and −145, including CLINT1, CDKN1A, IRS1, MAPK7, PPM1D and SOD2." (PMID 23782521, 2013).
motor neuron degeneration (1 paper, 2023). "For instance, in patients of riboflavin transporter deficiency (RTD), a neurodegenerative disorder characterized by sensorineural deafness and motor neuron degeneration, MNs have lowered SOD2 expression." (PMID 38706516, 2023).
mycosis fungoides (1 paper, 2024). Classical mycosis fungoides is the most common type of mycosis fungoides (MF), a form of cutaneous T-cell lymphoma, and is characterized by slow progression from patches to more infiltrated plaques and eventually to tumors. "Similarly, mycosis fungoides manifests elevated expression levels of FABP5, S100A8, and SOD2." (PMID 38596682, 2024).
myelomeningocele (1 paper, 2025). Myelomeningocele is the most severe form of spina bifida. "Along these lines, investigation of SNPs within the SOD1 and SOD2 genes, yielded four SNPs in SOD1 (rs202446, rs202447, rs4816405, and rs2070424) and one SNP in SOD2 (rs5746105) that were significantly associated with myelomeningocele risk." (PMID 40666233, 2025).
myocarditis (1 paper, 2021). Myocarditis is a condition that is characterized by inflammation of the heart muscle (myocardium). "Meanwhile, MLT repressed the reduction of Sod2 mRNA levels caused by myocarditis." (PMID 34708067, 2021).
nephrotic syndrome (1 paper, 2020). A collection of symptoms that include severe edema, proteinuria, and hypoalbuminemia; it is indicative of renal dysfunction. "In addition, some studies showed that the serum anti-PLA2R antibody, anti-THSD7A antibody, anti-SOD2 antibody, and anti-ENO antibody were all negative in IMN patients with a low proportion of nephrotic syndrome at onset, high plasma albumin level, and high disease remission rate." (PMID 32117644, 2020).
neuropathy (1 paper, 2020). A disorder affecting the nervous system that manifests with pain, tingling, numbness, and/or muscle weakness. "Moreover, the downregulation of the antioxidant SOD2 was of particular interest because this effect has been previously associated with increased oxidative damage and a stronger neuropathy phenotype in animal DPN models." (PMID 32787975, 2020).
normal tension glaucoma (1 paper, 2009). "Results suggested that genetic variation in five of the candidate genes (RDX, SNX16, OPA1, SOD2 and CYP1B1) is unlikely to confer major risk to develop normal tension glaucoma in the German population." (PMID 19754948, 2009).
omphalocele (1 paper, 2018). Omphalocele is an embryopathy classified in the group of abdominal celosomias and is characterized by a large hernia of the abdominal wall, centered on the umbilical cord, in which the protruding viscera are protected by a sac. "NAC is a well-known antioxidant and its stimulating effect on the expression level of antioxidant genes (such as Cat and Sod2) and GSH level has been demonstrated in various experimental models, including chick omphalocele and hyperoxic mice lung." (PMID 30243020, 2018).
ovarian adenocarcinoma (1 paper, 2025). An adenocarcinoma that arises from the ovary. "Treatment with CUR alone significantly inhibited the growth of human ovarian adenocarcinoma SKOV-3/CDDP CDDP-resistant subline cells by inhibition the gene expression of the antioxidant enzymes (SOD1, SOD2, GPX1, CAT, and HO1), transcription factor NFE2L2 and signaling pathway (PIK3CA/AKT1/MTOR)." (PMID 39859517, 2025).
Ovarian cyst (1 paper, 2018). The presence of one or more cysts of the ovary. "Expression of SOD2 was located in the cytoplasm of epithelial as well as stromal cells in normal ovaries, in ovarian cysts, and malignant cells in PCOC at early and late stages." (PMID 30596106, 2018). "The current study observed the expression of antioxidant enzyme, SOD2, by the cells of ovarian cysts and malignant cells in PCOC at early and late stages." (PMID 30596106, 2018). "However, the staining for SOD2 expression was stronger in the cells of ovarian cysts and malignant cells in PCOC." (PMID 30596106, 2018).
parotid tumor (1 paper, 2021). "In qRT-PCR, mRNA expression levels of Sod2, heme oxygenase 1 (Ho-1) and glutathione reductase (Gr) were higher in the PMA type of parotid tumor tissue in comparison to healthy tissue." (PMID 34360635, 2021).
penile cancer (1 paper, 2015). A primary or metastatic malignant neoplasm that affects the penis. "SOD2 expression in more than 50% of cells was observed in 44.8% of primary penile carcinomas of the usual type." (PMID 25745358, 2015). "However, the relationship between SOD2 expression and penile cancer has not been addressed, mainly in terms of regional lymph node metastasis." (PMID 25745358, 2015).
penile tumor (1 paper, 2015). "The implication of SOD2 expression in thin penile tumors is uncertain and should be interpreted with caution because a limited number of cases in this particular setting were observed." (PMID 25745358, 2015).
periapical periodontitis (1 paper, 2025). Inflammation of the periapical tissue. "Polymorphisms in the SOD2 and SOD3 genes influenced the OHRQoL of patients with asymptomatic periapical periodontitis who are undergoing root canal treatment." (PMID 40261148, 2025). "Genetic polymorphisms in SOD2 and SOD3 genes can influence the OHRQoL response in patients with asymptomatic periapical periodontitis." (PMID 40261148, 2025). "Consequently, our study proposed the hypothesis that genetic polymorphisms in SOD2 (rs5746136, rs4880, and rs10370) and SOD3 (rs2855262 and rs13306703) could modulate the impact of OHRQoL in patients with asymptomatic periapical periodontitis." (PMID 40261148, 2025).
peripheral artery disease (1 paper, 2017). "Besides that, under the administration of superoxide dismutase-2 (SOD-2), miR-222 plays its protective role against peripheral artery disease by regulating p57 expression but not P27." (PMID 28127557, 2017).
Peritoneal Fibrosis (1 paper, 2019). Disorder characterized by a wide range of structural changes in PERITONEUM, resulting from fibrogenic or inflammatory processes. "Whereas the role of TNFAIP6 and ZC3H12A in peritoneal fibrosis have not been reported yet, superoxide dismutase 2 encoded by SOD2 is a mitochondrial antioxidant previously known to play a role in protection against peritoneal fibrosis." (PMID 30728376, 2019).
Pneumocystis pneumonia (1 paper, 2019). "Genotype SOD2 was observed only in Pneumocystis pneumonia patients while the genotype SOD1 was observed in both colonized and Pneumocystis pneumonia patients." (PMID 31681723, 2019).
primary biliary cholangitis (1 paper, 2020). Primary biliary cholangitis (PBC) is a chronic and slowly progressive cholestatic liver disease of autoimmune etiology characterized by injury of the intrahepatic bile ducts that may eventually lead to liver failure. "Our results suggest that hsa-miR-23b is involved in pathophysiology of primary biliary cholangitis through interleukin-12 signaling via regulation of CNN2, JAK1, LMNB1, MTAP, SOD2, and TCP1." (PMID 33036164, 2020).
psychological distress (1 paper, 2020). "In addition, WT-PBMCs showed a significant decrease in mitochondrial content and SOD2 level following exposure to psychological distress (p ≤ 0.001)." (PMID 32555260, 2020). "While short term or long-term psychological distress modestly affect the bioenergetic status of PBMCs, our WB data showed that short-term psychological distress significantly decreases the level of mitochondria content and of SOD2 and DJ-1, two key mitochondrial antioxidants." (PMID 32555260, 2020).
scrapie (1 paper, 2021). A fatal disease of the nervous system in sheep and goats, characterized by pruritus, debility, and locomotor incoordination. "In previous studies, a decrease in SOD2 gene expression or protein has been observed in animals infected with scrapie strains." (PMID 34735539, 2021). "Using SOD2 heterozygous knock-out and litter mate wild-type controls, we examined neuronal long-term potentiation, disease duration, pathology, and degree of spongiform change in mice infected with three strains of mouse adapted scrapie." (PMID 34735539, 2021). "Our results indicate that SOD2 reduction does not influence acute or long-term responses to three different scrapie prion strains." (PMID 34735539, 2021).
seminoma (1 paper, 2022). A radiosensitive malignant germ cell tumor found in the testis (especially undescended), and extragonadal sites (anterior mediastinum and pineal gland). "This time, a significant association between SOD2*TT genotype and the risk of seminoma development was observed (OR = 2.46, 95%CI: 1.12–5.41, p = 0.025; adjusted OR = 2.84, 95%CI: 1.20–6.74, p = 0.017), thus providing a more refined confirmatory analysis." (PMID 35205816, 2022). "The present study demonstrated the SOD2*TT genotype as a significant risk biomarker for seminoma development." (PMID 35205816, 2022). "Moreover, carriers of variant SOD2*TT genotype were at almost 3-fold increased risk of seminoma development." (PMID 35205816, 2022). "In addition, the carriers of the SOD2*TT genotype were at a higher risk of developing seminoma." (PMID 35205816, 2022). "NRF2 (rs6721961), GSTM3 (rs1332018), SOD2 (rs4880) and GPX3 (rs8177412) polymorphisms were assessed in 88 patients with testicular GCT (52 with seminoma) and 88 age-matched controls." (PMID 35205816, 2022).
sensorineural hearing loss (1 paper, 2023). "In sensorineural hearing loss, researchers found that FOXO3a-SOD2 pathway was inhibited along with an increasing ROS level." (PMID 37061707, 2023).
Shock (1 paper, 2015). The state in which profound and widespread reduction of effective tissue perfusion leads first to reversible, and then if prolonged, to irreversible cellular injury. "First, we confirmed that SIRT1 protein level and activity were decreased in the setting of intestinal injury after severe hemorrhagic shock and reperfusion, and these changes may be related to alterations in the SIRT1-PGC-1α-SOD2 axis signaling pathway." (PMID 26301045, 2015).
sialadenitis (1 paper, 2024). Sialadenitis is an infection of the salivary glands. "At the later time point, both i-sg-Sod2 KO and control littermates showed higher severity and incidence of sialadenitis." (PMID 38892170, 2024).
sideroblastic anemia (1 paper, 2011). "Reconstitution of mice with hematopoietic stem cells deficient in manganese superoxide dismutase (SOD2) results in a hemolytic anemia that recapitulates many features seen in patients with sideroblastic anemia (SA)." (PMID 21326867, 2011). "Mice irradiated and reconstituted with hematopoietic cells lacking manganese superoxide dismutase (SOD2) show a persistent hemolytic anemia similar to human sideroblastic anemia (SA), including characteristic intra-mitochondrial iron deposition." (PMID 21326867, 2011). "Novel insights into pathogenesis of sideroblastic anemia may come from evaluation of the function of additional candidate genes identified as strongly differentially expressed between normal and Sod2-/- erythroblasts, but with no previously defined role in erythroid development." (PMID 21326867, 2011).
silicosis (1 paper, 2019). Silicosis is a respiratory disease caused by breathing in (inhaling) silica dust. "In addition, some oxidizing enzymes (iNOS, SOD2, and XO) were also significantly elevated in mice silicosis model." (PMID 31273057, 2019).
skin aging (1 paper, 2022). The gradual irreversible changes in structure of skin that occur as a result of the passage of time.. "Although these results were for blood, they support the possibility that SOD3 expression, but not SOD1 and SOD2, is significantly altered with skin aging." (PMID 35624792, 2022).
social phobia (1 paper, 2023). An anxiety disorder characterized by an intense, irrational fear of one or more social or performance situations in which the individual believes that he or she will be scrutinized by others. "We also observed statistically significant associations between SOD2 rs4880 and obsessive–compulsive symptoms, PON1 rs705381 and social phobia, IL1B rs1071676 and AUDIT scores, and IL6R rs2228145 and compulsions in alcohol-addicted patients." (PMID 38275640, 2023).
soft tissue sarcoma (1 paper, 2021). A malignant neoplasm arising from muscle tissue, adipose tissue, blood vessels, fibrous tissue, or other supportive tissues excluding the bones. "Notably, high levels of SOD2 and GPx contribute to therapeutic resistance in soft tissue sarcoma." (PMID 33562681, 2021).
spinal cord ischemia (1 paper, 2022). Reduced blood flow to the spinal cord which is supplied by the anterior spinal artery and the paired posterior spinal arteries. "In a spinal cord ischemia model, MMP loss and neuronal apoptosis were protected by ZL006 by stimulating SOD2 deacetylation and mitochondrial enzyme activities in a SIRT3-dependent manner." (PMID 35372451, 2022).
squamous cell carcinomas of the penis (1 paper, 2015). "SOD2 protein expression levels were determined by immunohistochemistry in 125 usual type squamous cell carcinomas of the penis from a Brazilian cancer center." (PMID 25745358, 2015).
systemic sclerosis (1 paper, 2023). A chronic disorder, possibly autoimmune, marked by excessive production of collagen which results in hardening and thickening of body tissues. "A gene array analysis showed increased NOX4 gene expression and decreased SOD2 expression in systemic sclerosis (SSc) and IPF lung fibroblasts compared to non-fibrotic controls." (PMID 37686037, 2023).
T-cell lymphoma (1 paper, 2016). "Even though in a mouse model of T-cell lymphoma, SOD2 has a tumor suppressor effect, it was demonstrated that in HIV-infected HUT-78 cells, overexpression of SOD2 may have a tumor-supportive function due to the fact that it increases resistance to heat and radiation." (PMID 27821903, 2016).
tendinopathy (1 paper, 2023). "Moreover, SOD2 is a mitochondrial isoform that has been associated with mitochondrial dysfunction linked to development of tendinopathy." (PMID 37686103, 2023). "Notably, the increased SOD2 levels that were only observed in the presence of PRP may help to restore tendon homeostasis, as SOD2 gene expression and SOD activity has been described in a murine model of tendinopathy." (PMID 37686103, 2023).
thrombosis (1 paper, 2022). "We identified Sod2 as an essential mediator of the circulating neutrophils in offsetting intravascular ROS and suppressing thrombosis." (PMID 35933512, 2022).
thyroid (1 paper, 2020). "Both SOD1 and SOD2, which catalyze the dismutation of superoxide radicals into less reactive hydrogen peroxide and oxygen, were significantly higher expressed in the thyroid lesions compared to TN." (PMID 32603365, 2020).
viral hepatitis (1 paper, 2015). An acute or chronic inflammation of the liver parenchyma caused by viruses. "To investigate whether SOD enzymes contribute to viral hepatitis, we infected Sod1−/−, Sod2+/−—a commonly used model for Sod2 deficiency —and Sod3−/− mice with LCMV and monitored the course of disease." (PMID 26588782, 2015).
X-linked sideroblastic anemia with ataxia (1 paper, 2011). A rare syndromic, inherited form of sideroblastic anemia in which the cause of the disease is a mutation in the ABCB7 gene and is characterized by mild to moderate anemia (with hypochromia and microcytosis) and early-onset, non- or slowly progressive spinocerebellar ataxia. "ABCb7, previously shown to be mutated in X-linked sideroblastic anemia with ataxia (XLSA/A—OMIM 301310) is decreased in Sod2-/- cells (1.6 fold decrease, p = 0.02, unpaired t test)." (PMID 21326867, 2011).